FAAH (fatty acid amide hydrolase)
Diseases named in the same sentence as FAAH in open-access papers (continued):
Sharing a sentence is not in itself a finding about the gene and the disease.
Obesity (continued). "According to the study outcomes of Mansouri and colleagues (2020), individuals with the FAAH genetic variant C385A not only may be prone to developing obesity, but they could also present a greater vulnerability for addiction, due to the higher expression level of dopamine D3 receptors in the brain." (PMID 41096816, 2025). "However, a number of studies in mice and men reported on a diminished FAAH expression found in adipose tissue of obese subjects, although other groups found unchanged or even increased FAAH expression associated with obesity." (PMID 28859076, 2017). "Functional in-vitro studies further revealed that expression and activity of FAAH is reduced in isolated peripheral circulating T-lymphocytes of homozygotes for the rs324420 A-allele, thus seemingly underlining the observed association of rs324420 with obesity." (PMID 20044928, 2010). "The main research question here was whether quantitative measurement of plasma endocannabinoids, anandamide, and related N-acylethanolamines (NAEs), combined with genotyping for mutations in fatty acid amide hydrolase (FAAH) would identify circulating biomarkers of ECS activation in severe obesity." (PMID 20098695, 2010). "This study aims to analyze the association between the dinner GI and the C385A variant in the FAAH gene with respect to fasting glucose, insulin levels, and HOMA-IR in adults with obesity." (PMID 41750344, 2026). "Both animal and human studies have suggested that targeting FAAH activity is a potential therapeutic strategy for treating obesity." (PMID 38812531, 2024). "In summary, our study highlights the superior anti-obesity effects of dietary DMS compared to 4-desmethylsterols through the inhibition of FAAH-1 activity." (PMID 38812531, 2024). "Despite the progress recently, the withdrawal of the FAAH inhibitor during clinical trial and anti-obesity CB1R antagonist due adverse effects engenders cautionary approaches in clinical trials." (PMID 35774086, 2022). "We identified 30 studies that included association between a FAAH or MGLL gene variant and any obesity-related outcome in a human sample." (PMID 34959715, 2021). "Three studies used bioinformatic approaches to identify novel genetic variants in FAAH and MGLL genes associated with obesity or obesity-related traits." (PMID 34959715, 2021). "While our review considered only candidate gene association studies in humans involving FAAH or MGLL, a brief note on genome-wide association studies (GWAS) of obesity is worthwhile." (PMID 34959715, 2021). "The following terms were used in a Boolean search format: (FAAH OR “Fatty acid amide hydrolase” OR MAGL OR MGL OR “Monoacylglycerol lipase” OR DAGL OR DGL OR “Diacylglycerol lipase”) AND (obesity)." (PMID 34959715, 2021). "This review aims to synthesize all studies investigating pharmacological or genetic manipulation of FAAH, MAGL, or DAGL enzymes in association with obesity-related measures." (PMID 34959715, 2021). "A polymorphism impairing expression of fatty acid amide hydrolase (FAAH), the enzyme responsible for degrading AEA, correlated with severity of both insulin resistance and obesity." (PMID 31156558, 2019). "Another polymorphism positively associated with obesity is the FAAH polymorphism rs324420 that reduces FAAH activity, leading to higher AEA levels and consequent over-activation of CB1 receptors, which, in turn, causes adipogenesis and a high obesity risk." (PMID 31771129, 2019). "Studies also have reported that a down-regulation of fatty acid amide hydrolase (FAAH), the enzyme that degrades AEA and other N-acylethanolamines, is associated to obesity." (PMID 26849214, 2016). "FAAH in adipocytes is differentially altered in animal models of obesity and diabetes, while MGL activity is increased by both." (PMID 24593280, 2014).
Obesity (continued). "Both insulin resistance and metabolic inflexibility have been described as co-incident in obesity, therefore we examined metabolic inflexibility and energy expenditure in FAAH−/− mice by indirect calorimetry." (PMID 22442717, 2012). "Several human studies reported that CB1 and FAAH gene expression in visceral and subcutaneous adipose tissue were decreased with obesity and the expression levels were negatively related to visceral fatness." (PMID 22035053, 2011). "There are no obvious reasons as to why discrepancies have been reported with regard to FAAH expression levels in adipose tissue in obesity." (PMID 21813022, 2011). "The increased levels of AEA and 2-arachidonoylglycerol (2-AG), another arachidonic acid-derived endocannabinoid, have led to the concept of the 'overactivated' endocannabinoid system in obesity in which FAAH expression is reduced." (PMID 20546561, 2010). "The expression of FAAH and MGLL in numerous tissues will make it challenging to determine the exact role that the regulatory variants identified in our study play in obesity." (PMID 21118518, 2010). "This study achieved the aim of identifying both plasma and FAAH gene ECS biomarkers of severe obesity that have the potential to be clinically useful if confirmed by larger studies." (PMID 20098695, 2010). "Analyses of five SNPs in FAAH in up to 521 German obesity trios and 235 independent obesity families revealed nominal evidence for association of two FAAH SNPs (rs324420 and rs2295632) with early onset extreme obesity." (PMID 20044928, 2010). "In this study, we generated high quality sequencing data to analyze the association of DNA variants in two candidate genes, FAAH and MGLL, with extreme obesity." (PMID 21118518, 2010). "In this report, we explore the genetic diversity of 188 kb of sequence encompassing the FAAH and MGLL genes in 289 individuals and use variants from the whole allelic frequency spectrum to investigate association with extreme obesity (BMI ≥40 kg/m2)." (PMID 21118518, 2010). "Notably, FAAH expression is upregulated by a high-fat diet, whereas treatment with germinated soy germ extract, which exhibits anti-obesity properties, reduces FAAH expression." (PMID 41155164, 2025). "Reduced FAAH activity has been demonstrated to lower food intake, increase energy expenditure, and improve insulin sensitivity, all of which contribute to the development of abnormal fat accumulation and obesity." (PMID 38812531, 2024). "Consequently, 4,4-dimethylsterols represent an unexplored class of beneficial phytosterols that coordinate with FAAH-1 activity to reduce fat accumulation, which offers new insight into intervention strategies for treating diet-induced obesity." (PMID 38812531, 2024). "Genetic factors, such as the FAAH 385 A/A missense polymorphism, which reduces FAAH enzymatic activity, may also contribute to ECS dysregulation in obesity." (PMID 39292202, 2024). "This suggests that variation in ECS genes is unlikely to make a major contribution to polygenic obesity, which is in line with the heterogeneity in results of candidate gene association studies (FAAH and obesity outcomes) we reviewed here." (PMID 34959715, 2021). "On the other hand, we found reports that presented contradictory results, suggesting that FAAH gene polymorphism and mutant allele carrying were not related to overweight or obesity." (PMID 33530406, 2021). "While our review has not provided clear evidence that FAAH or MAGL inhibitors would be useful for treating obesity, it will be worth noting whether there are any weight- or obesity-related effects observed in FAAH and/or MAGL inhibitor trials." (PMID 34959715, 2021). "Monitoring changes in body weight in ongoing clinical trials of FAAH inhibitors may clarify whether FAAH inhibition is a potential therapeutic strategy for treatment obesity." (PMID 34959715, 2021). "This is in line with the fact that FAAH was reported to play an important role in obesity." (PMID 30687125, 2018).
Obesity (continued). "Conflict exists within the literature with respect to FAAH activity in obesity." (PMID 25874237, 2015). "Since FAAH is regulated by both insulin and leptin, we hypothesise that factors such as insulin and leptin resistance in obesity oppose any further increases in FAAH activity and that MGL must be under other regulating factors." (PMID 24593280, 2014). "An increase in FAAH activity in adipocytes with increasing BMI may simply be part of this general upregulation of ECS tone in obesity." (PMID 21813022, 2011). "However, other studies reported no changes in CB1 gene expression in visceral and subcutaneous adipose tissue, or even elevated CB1 and FAAH gene expression in visceral and subcutaneous adipose tissue with obesity." (PMID 22035053, 2011). "The techniques used in these studies appear to have been similar, as do the subjects sampled, although females are represented more than males in the studies showing FAAH to be downregulated in obesity, and males are a larger proportion of the results showing FAAH to be upregulated." (PMID 21813022, 2011). "In summary we observed some evidence for an association of two SNPs in FAAH (rs324420 and rs2295632) with early onset but not adult obesity." (PMID 20044928, 2010). "While evidence points to a genetic association of these loci with obesity, multiple recent studies using common SNPs in the FAAH region have failed to confirm an association." (PMID 20976246, 2010). "In addition, we show the association of a rare locus-variant in the FAAH promoter with increased plasma levels of AEA, thus providing an independent validation of the genetic association with obesity." (PMID 21118518, 2010). "Furthermore, HFD-induced obesity has been shown to modulate FAAH expression in various tissues." (PMID 40474970, 2025). "In several published studies, FAAH mRNA levels in adipose tissue have been compared between lean and obese humans, and there is conflict over whether FAAH is up- or down-regulated in adipose tissue in obesity." (PMID 21813022, 2011). "As we observed some evidence for an association of the FAAH variants rs2295632 rs324420 with early onset but not adult obesity, we conclude that the FAAH variants analyzed here at least do not seem to play a major role in the etiology of obesity within our samples." (PMID 20044928, 2010). "Thus, FAAH and MGLL are excellent candidates to be sequenced in the extreme of the BMI distribution to find the extent of their genetic diversity and potential association of variants with obesity." (PMID 21118518, 2010). "Moreover, FAAH variants were not reported among the top-hits of recent meta-analyses of genome-wide association studies for BMI or obesity; potentially also indicating their minor importance for the etiology of obesity." (PMID 20044928, 2010). "Dysregulation of FAAH and MAGL activity can lead to altered endocannabinoid signaling, contributing to conditions like chronic pain, obesity, and metabolic disorders." (PMID 40474970, 2025). "Here, we aimed to investigate the effects of DMS on FAAH activity using various models, including C. elegans, THLE-2 cells, and a mouse model of high-fat diet (HFD)-induced obesity." (PMID 38812531, 2024). "Accordingly, PLA2G2A and PLA2G4A genes were up-regulated by omega-3 polyunsaturated fatty acids supplementation, whereas SLC27A2, CNR1, DAGLA, MGLL, FAAH, SLC27A1, and SLC27A2 genes were found to be down-regulated in people living with healthy obesity." (PMID 38024342, 2023). "As such, HFD-induced obesity increased CB1, ghrelin receptor and fatty acid amide hydrolase (FAAH) mRNA content in the NG, contributing to a reduction of vagal afferent sensitivity." (PMID 37571301, 2023). "scWAT gene expression of SLC27A2, CNR1, DAGLA, MGLL, FAAH, SLC27A1 and SLC27A2 were lower in individuals living with healthy obesity." (PMID 38024342, 2023). "We identified 5 animal studies that administered a pharmacological inhibitor of FAAH or DAGL and measured an obesity-related outcome." (PMID 34959715, 2021).
Obesity (continued). "Although SNPs were located on obesity-related genes, some of the genes also have a direct role in lipid metabolism including PPARG, FABP2, PLIN1, NPC1, ACSL5, and FAAH, suggesting relationships between genetics, adiposity, and plasma lipid profiles." (PMID 30581838, 2018). "A recent study has shown that obesity and high fat dietary intake influences CB1 receptor expression in skeletal muscle and FAAH gene expression in subcutaneous adipose tissue." (PMID 25874237, 2015). "MGL activity was raised in both the obese and obese diabetic rats suggesting a differential regulation of FAAH and MGL in diabetes in obesity." (PMID 24593280, 2014). "The results presented in this study show that FAAH and MGL enzyme activities are increased in adipocytes from animal model of diabetes/obesity." (PMID 24593280, 2014). "We applied RareCover to determine if multiple RVs, i.e., allelic heterogeneity, mediated the genetic effects of FAAH and MGLL on obesity." (PMID 20976246, 2010). "Upon suppression/inhibition of the FAAH or MAGL enzymes, endocannabinoid levels are elevated, and hyperphagia, leptin resistance, and obesity may develop." (PMID 36830844, 2023). "Modulating the enzymes that synthesize and degrade endocannabinoids, namely fatty acid amide hydrolase (FAAH), monoacylglycerol lipase (MAGL), and diacylglycerol lipase (DAGL), may be a promising strategy to treat obesity." (PMID 34959715, 2021). "A review of these data found no SNPs in FAAH, MGLL, or DAGLA/DAGLB that showed genome-wide significant association (p < 5 × 10−8) with obesity or related outcomes (no SNPs in CNR1 either)." (PMID 34959715, 2021). "Taken together, the reviewed body of literature provides a mixed picture of whether FAAH, MAGL, or DAGL are likely to be druggable targets for obesity treatment." (PMID 34959715, 2021). "The primary aim of this study was to determine whether the activities of FAAH and MGL, two key catabolic enzymes of the ECS, are differentially affected by diabetes or other markers of the metabolic syndrome in obesity." (PMID 24593280, 2014). "Our application of the method on the CRESCENDO individuals, generates plausible hypotheses on the role of FAAH and MGLL in of obesity." (PMID 20976246, 2010). "Thus, based on the evidence reviewed, FAAH inhibition is not likely a promising approach for obesity treatment." (PMID 34959715, 2021). "There are reported changes in obesity of blood concentrations of the endocannabinoids anandamide (AEA) and 2-arachidonoylglcyerol (2-AG), and of adipose tissue expression levels of the two key catabolic enzymes of the ECS, fatty acid amide hydrolase (FAAH) and monoacylglycerol lipase (MGL)." (PMID 21813022, 2011). "Thus, the goal of the present review was to systematically review the published empirical literature and qualitatively synthesize existing evidence that either pharmacological or genetic manipulation/variation of FAAH, MAGL, and DAGL might impact obesity-related outcomes." (PMID 34959715, 2021). "Our findings provide evidence for an endocannabinoid-related phenotype that may be identified by the combination of circulating anandamide levels with genotyping of the FAAH 385C>A; this phenotype is not exclusive to mono-ethnoracial populations nor to individuals with severe obesity." (PMID 26561012, 2015). "By detecting eCB levels in obese patients, it was found that although diet and obesity had no influence on eCB levels, expression of DAGL was upregulated, while mRNA expressions of MAGL and FAAH were downregulated in subcutaneous adipose tissue." (PMID 36830844, 2023). "There is no current evidence published on drugs modulating NAPE-PLD, FAAH, and MAGL expression with anti-obesity-like effects, even though several molecules have been developed to treat CNS-related pathologies." (PMID 34681224, 2021).
migraine (29 papers, 2016 to 2025). "Thus, the selective enhancement of 2-AG and AEA via MAGL and FAAH inhibition, respectively, can provide a beneficial reduction of pain triggering, transmission and excessive cortical excitability, underlying migraine pathophysiology." (PMID 35457225, 2022). "In this regard, one intriguing issue is whether the profile of MAGL/FAAH activity is different in the trigeminal ganglia (TG) implicated in migraine and dorsal root ganglion (DRG) involved in the transmission of somatic and visceral pain." (PMID 33530477, 2021). "However, activities of MAGL and FAAH were comparably high in the cerebellum and cerebral cortex implicated in migraine aura." (PMID 33530477, 2021). "Numerous studies have shown that FAAH inhibition causes analgesia and reduces inflammation in animal models of acute inflammatory pain, but there is little information on their effects in migraine." (PMID 29615860, 2018). "Utilizing a NTG rat migraine model, systemic administration of the peripherally restricted FAAH inhibitor URB937 served to block NTG-induced hyperalgesia, supporting the involvement of AEA in the mitigation of migraine pain." (PMID 40630421, 2025). "Further, activity levels for female ETTH patients were the same as female controls, but both EMT and FAAH activity levels were significantly higher in migraine patients than female controls." (PMID 40630421, 2025). "Review papers have emphasized the importance of peripheral FAAH inhibition as a possible therapeutic avenue for migraine pain." (PMID 41155546, 2025). "Targeting FAAH-regulated AEA signaling has potential in the development of new agents against migraine pain." (PMID 41155546, 2025). "Our results confirmed the anti-allodynic effect of the Hsp90 inhibitor 17-AAG in a preclinical model of migraine by modulation of the FAAH-NAPE-PLD-AEA system in PAG." (PMID 41155546, 2025). "Altogether, these results, obtained in a migraine-specific animal model, suggest that the dual inhibition of FAAH/MAGL activity has a role in the pathophysiology of migraine." (PMID 38786051, 2024). "The present findings show for the first time the in vivo potential of the dual MAGL/FAAH inhibitor AKU-005 to counteract several of the NTG-induced effects that are relevant to migraine, probably by modulating the CGRP pathway." (PMID 38786051, 2024). "Endocannabinoids degrading enzymes monoacylglycerol lipase (MAGL) and fatty acid amide hydrolase (FAAH) have been found distinctly active in the main areas involved in migraine pain signaling." (PMID 39407099, 2024). "In agreement, in a previous study, FAAH gene expression in the peripheral cells was significantly lower in migraine patients than in control subjects." (PMID 37138206, 2023). "This compound showed high FAAH inhibitory selectivity and efficiency in vitro in areas involved in migraine aura, namely the cerebellum and cerebral cortex." (PMID 37373250, 2023). "Taken together, our findings suggest that the AEA/FAAH pathway holds a promise for inhibiting migraine-related pathological meningeal neuronal hyperexcitability via CB1 receptors and potentially affecting TRPV1 receptors." (PMID 37038131, 2023). "In conclusion, dual MAGL/FAAH inhibitor AKU-005 represents a promising compound to counteract migraine nociception, which originates from the trigeminal nociceptive system that includes the meninges." (PMID 37038131, 2023). "Together with previously detected MAGL activity in trigeminal ganglia, dual MAGL/FAAH inhibitor AKU-005 appears promising as migraine treatment." (PMID 37038131, 2023). "Although the precise mechanism underlying these effects remains to be elucidated, our results support further investigational studies of FAAH blockade as a potential therapeutic strategy to treat migraine conditions." (PMID 35799128, 2022).